TSLP (thymic stromal lymphopoietin)
Diseases named in the same sentence as TSLP in open-access papers (continued):
Sharing a sentence is not in itself a finding about the gene and the disease.
leukemia (8 papers, 2015 to 2025). A malignant (clonal) hematologic disorder, involving hematopoietic stem cells and characterized by the presence of primitive or atypical myeloid or lymphoid cells in the bone marrow and the blood. "The identification of IGF1R and FGFR1 as novel components of TSLP/CRLF2 signaling enhances our understanding of the molecular mechanisms that underlie TSLP-mediated leukemia proliferation." (PMID 40787610, 2025). "By targeting TSLP and its receptor, key cellular signaling pathways can be disrupted, inhibiting leukemia cell growth and spread, thus providing new therapeutic options and hope for high-risk leukemia patients." (PMID 40787610, 2025). "Therefore, we conclude that the RAS isoform activity pattern of TSLP-inducibility in wtRAS leukemia cells matches the isoforms that acquire mutations in RAS-mutated leukemia cases." (PMID 33247204, 2021). "Given that the normal physiological levels of TSLP in children (13–32 pg/mL) are relatively low, it is suggested that during the development of leukemia, TSLP primarily promotes tumor cell proliferation at low levels." (PMID 40787610, 2025). "•First demonstration of TSLP's dual roles in leukemia: TSLP promotes proliferation via CRLF2 signaling while inducing apoptosis in specific contexts, revealing its paradoxical tumor-modulating effects." (PMID 40787610, 2025). "TSLP promotes leukemia cell proliferation primarily through its receptor (TSLPR), encoded by the CRLF2 gene, and the downstream JAK-STAT signaling pathway." (PMID 40787610, 2025). "Although targeting TSLPR has shown efficacy to some extent, TSLP-independent mechanisms play a crucial role in leukemia proliferation." (PMID 40787610, 2025). "In CRLF2 B-ALL, TSLP plays a dual role in leukemia cell proliferation, closely related to its dosage." (PMID 40787610, 2025). "It has been shown that TSLP promotes leukemia proliferation by regulating different signaling pathways." (PMID 40787610, 2025). "Recent studies have elucidated the diverse signaling mechanisms activated by TSLP in leukemia cells, with a particular focus on CRLF2-overexpressing Ph-like ALL cell lines." (PMID 40787610, 2025). "By meticulously investigating the relationship between TSLP dosage and its biological effects, we can establish a robust foundation for the precise treatment of leukemia." (PMID 40787610, 2025). "Additional studies demonstrated that TSLP stimulation of CRLF2-rearranged leukemia cells resulted in aberrant STAT5 and PI3K/mTOR pathway signaling." (PMID 40787610, 2025). "These kinases activate downstream proliferation-related pathways, highlighting the critical role of MAPK signaling in TSLP-mediated leukemia proliferation." (PMID 40787610, 2025). "This review focuses on the dual mechanisms of TSLP in leukemia, providing new insights for leukemia treatment." (PMID 40787610, 2025). "Together, these findings indicate that the leukemia-cell death that occurs in vitro in response to high concentrations of TSLP also occurs in vivo." (PMID 36613920, 2022). "We detected that mice treated with high doses of TSLP showed a significant decrease (p = 0.0006, 0.0025, 0.001, and <0.0001 for weeks 2, 3, 4, and 5, respectively) in leukemia burden, when compared to those treated with low doses of TSLP." (PMID 36613920, 2022). "Despite the need for human TSLP, we and others observed engraftment of primary JAK2 mutated cells in NSG mice, giving rise to leukemia within months after intra-femoral injection." (PMID 29163799, 2017). "This suggests that TSLP's impact on leukemia, particularly ALL, may be significantly influenced by the timing of its expression." (PMID 40787610, 2025). "However, it has also shown that other gene mutations can occur during this proliferative process, making it impossible to completely cure leukemia by targeting TSLP alone." (PMID 40787610, 2025).
leukemia (continued). "TSLP may promote leukemia cell proliferation through several signaling pathways, including JAK-STAT, PI3K/mTOR, and MAPK, as well as through other factors such as RAS, IGF1R, and FGFR1." (PMID 40787610, 2025). "Targeting TSLP and its receptor using approaches such as CAR T-cell therapy and JAK inhibitors has emerged as a promising strategy for treating high-risk leukemia patients." (PMID 40787610, 2025). "RNA sequencing (RNA-seq) and quantitative PCR (qPCR) analyses of the xenograft tumors confirmed the expression of mTOR-regulated genes in primary CRLF2 B-ALL cells, substantiating the involvement of the PI3K/mTOR pathway in TSLP/TSLPR-mediated leukemia proliferation." (PMID 40787610, 2025). "Additionally, considering the individual TSLP levels and leukemia subtypes in patients will be crucial in selecting appropriate therapeutic approaches to further enhance treatment efficacy." (PMID 40787610, 2025). "This phenomenon highlights that TSLP's role in leukemia might vary depending on the developmental stage." (PMID 40787610, 2025). "The reduced spleen weights and prolonged survival of PDX-1 mice treated with high doses of TSLP indicated that TSLP may reduce the number of leukemia cells (tumor burden) in the xenograft mice and prolong the survival of the mice." (PMID 36613920, 2022). "In this study we investigated whether treatment of pre-clinical models of CRLF2 B-ALL, both cell lines and PDXs, with increasing concentrations of TSLP has major effects on leukemia cell survival in vitro and leukemia burden in vivo." (PMID 36613920, 2022). "Additionally, effect of TSLP on leukemia was found to be dose dependent." (PMID 40787610, 2025). "Furthermore, it was observed that they are increased by TSLP in leukemia models." (PMID 38557942, 2024). "We next assessed the induction of phosphorylated (p) STAT5, ERK, and Akt in response to short-term TSLP stimulation in CRLF2R and CRLF2NR leukemias." (PMID 31318944, 2019). "Thymic stromal-derived lymphopoietin (TSLP), the ligand binding to CRLF2, induces leukemia proliferation involving mTOR signaling and cases of Ph-like ALL with aberrant CRLF2 expression displayed increased mTOR signaling activity." (PMID 25682198, 2015). "In the context of leukemia, particularly ALL, TSLP exhibits a complex dual role." (PMID 40787610, 2025). "We treated these leukemias with the combination of DEX and inhibitors of JAK1/2 (ruxolitinib), MEK (trametinib), or Akt (MK2206) at concentrations that attenuated TSLP-induced signaling in the CRLF2R Ph-like ALL cell line Mutz-5 and that did not demonstrate toxicity in healthy PBMCs." (PMID 31318944, 2019). "Four of 10 CRLF2R leukemias, including two that lacked a concomitant JAK2 mutation, markedly induced pSTAT5 in response to short-term TSLP stimulation, while CRLF2NR leukemias did not." (PMID 31318944, 2019). "The emergence of a stronger dependency between prpS6 and pCREB in the MRD cells compared to that in the total leukemia population at diagnosis is similar to that observed in the STAT5-non-responsive TSLP cells." (PMID 29796158, 2018). "This indicates that directly targeting TSLP alone may be insufficient to completely cure leukemia, possibly because TSLP is non-essential for leukemia cell proliferation." (PMID 40787610, 2025). "Although targeting TSLPR has proven to be an effective strategy for inhibiting leukemia cell proliferation, some studies suggest that TSLP might not play a significant role in promoting leukemia cell growth and may even have opposing effects." (PMID 40787610, 2025). "Thus, administering high levels of TSLP may offer a novel therapeutic strategy for treating CRLF2 B-ALL, providing new insights into clinical leukemia treatment." (PMID 40787610, 2025).
leukemia (continued). "Finally, using our novel +TSLP patient-derived-xenograft (PDX) mouse model, we showed that high doses of TSLP prevented the engraftment of primary CRLF2 B-ALL cells, decreased the leukemia burden, and prolonged the survival of CRLF2 B-ALL xenograft mice." (PMID 36613920, 2022). "However, some studies indicate that TSLP may not be essential for leukemia proliferation, with high concentrations of TSLP potentially inducing apoptosis in CRLF2 B-ALL cells." (PMID 40787610, 2025). "CRLF2R leukemias also induced pERK and pAkt in response to TSLP, with no induction in the CRLF2NR leukemias (p = 0.001 and p = 0.002 versus CRLF2NR leukemias, respectively)." (PMID 31318944, 2019).
ulcerative colitis (8 papers, 2019 to 2025). An inflammatory bowel disease involving the mucosal surface of the large intestine and rectum. "Reduced TSLP levels have been associated with Th1-driven diseases (e.g., Crohn’s disease), whereas elevated levels are characteristic of Th2-driven conditions (e.g., ulcerative colitis)." (PMID 40981017, 2025). "Clinical studies found that the mRNA expression level of TSLP was significantly lower in ulcerative colitis patients than in the control group, and the low expression of TSLP showed a positive correlation with the severity of ulcerative colitis." (PMID 36806964, 2023). "In the present study, we investigated the relative gene expression levels of TSLP and IL-33 molecules in ulcerative colitis." (PMID 30868311, 2019). "TSLP expression is found to be reduced in patients with ulcerative colitis compared with controls, and TSLP level is inversely correlated with disease severity, which may suggest that TSLP is a protective signal in this disease." (PMID 37427591, 2023).
Autoimmunity (7 papers, 2015 to 2024). The occurrence of an immune reaction against the organism's own cells or tissues. "In line with these mouse data, in the DC/T-cell co-cultures we observed potent additive effects of IL-7 and TSLP on production of Th17-associated cytokines IL-17, IL-21 and IL-22 that can strongly stimulate autoimmunity." (PMID 26110994, 2015). "The local production of TSLP by hepatocytes as well as keratinocytes causes a significant increase in its systemic concentrations, a step sufficient to promote a break in B-cell homeostasis and likely to induce B-lineage-dependent autoimmunity." (PMID 25889007, 2015). "This is the first study to assess the combined roles of IL-7 and TSLP in autoimmunity and shows that both cytokines play a specific pro-inflammatory role during experimental arthritis." (PMID 26110994, 2015). "Additionally, TSLP in allergic inflammation may result in a reduction in B cell tolerance and has been found to promote B lineage-dependent autoimmunity." (PMID 36851770, 2023). "Thymic stromal lymphopoietin (TSLP), an epithelial alarmin, has recently been demonstrated to have significant pathophysiological roles in a number of pulmonary and systemic disorders such as allergic pulmonary inflammation, cancer and autoimmunity." (PMID 34418598, 2021).
chronic asthma (7 papers, 2013 to 2025). An asthma that is characterized by the development of persistent airway inflammation and recurrent attacks of breathlessness and wheezing, which vary in severity and frequency. "Other secondary outcomes, also related with the association of nasal TSLP and periostin with the long-term respiratory morbidity, were evaluated, mainly need of chronic asthma treatment and respiratory admissions during the follow-up period." (PMID 36694181, 2023). "Our findings thus support a critical function for TSLP in sustaining the Th2-IgE axis in chronic asthma." (PMID 41259396, 2025). "Consistently, TSLP levels were markedly elevated in chronic asthma and declined during remission, detected in lung tissue, BALF, and serum." (PMID 40503233, 2025). "In mouse models of chronic asthma, TSLP inhibition improved airway remodeling features, such as peribronchial collagen deposition and goblet cell hyperplasia." (PMID 41169790, 2025). "TSLP conditioned the immune system to induce a robust Th2 response, initiating chronic airway inflammation and structural remodeling in mice with chronic asthma." (PMID 23300949, 2013). "Beyond T2 inflammation, TSLP promotes airway remodeling, by inducing bronchial smooth muscle cell migration and proliferation, contributing to bronchial wall thickening and remodeling in chronic asthma." (PMID 41169790, 2025).
gastric cancer (7 papers, 2018 to 2025). A primary or metastatic malignant neoplasm involving the stomach. "Higher tissue expression of TSLP and higher circulating levels of this cytokine were associated with a poor prognosis of gastric cancer." (PMID 40873585, 2025). "TSLP mRNA was overexpressed in the majority of gastric cancer patients compared to distant tumor-free samples." (PMID 40873585, 2025). "In gastric cancer patients TSLP expression in the tumor correlated with worse prognosis, and high serum concentration of TSLP was identified as an independent prognostic factor of reduced survival." (PMID 33042121, 2020). "Recent studies have suggested that TSLP contributes to the development of malignant tumors such as Hodgkin disease, pancreatic, cervical, breast, and gastric cancers." (PMID 31023965, 2019). "Moreover, in gastric cancer, TSLP is closely related to tumor progression and poor survival." (PMID 30214685, 2018). "Moreover, it will be important to assess whether TSLP expression or/and serum levels could serve as prognostic factors for cutaneous melanoma patients, as recently reported in gastric cancer, oropharyngeal squamous cell carcinoma, or epithelial ovarian carcinoma." (PMID 36107619, 2022).
allergic conjunctivitis (6 papers, 2016 to 2025). "TSLP can activate mast cells to secrete IL-13, a cytokine that plays a pathophysiological role in allergic conjunctivitis." (PMID 38541674, 2024). "Allergic conjunctivitis to Short Ragweed pollen required TLR4 to drive the production of TSLP/OX40L and the priming of a productive Th2 response." (PMID 31164097, 2019). "The tear TSLP, IL-4, IL-5, and IL-13 expression levels in different types of allergic conjunctivitis were found elevated to varying degrees in the VKC, SAC, and PAC compared with the control group; the differences were statistically significant (P < 0.001)." (PMID 27504196, 2016). "The conjunctival tissues of various types of allergic conjunctivitis displayed stronger TSLP, IL-4, IL-5, and IL-13 staining throughout the entire epithelium than did those of normal controls." (PMID 27504196, 2016). "In short, although in the past animal models of allergic conjunctivitis were used, normal corneal epithelial cell culture studies on the role and mechanisms of TSLP in the pathogenesis of allergic conjunctivitis played an irreplaceable role." (PMID 27504196, 2016). "The current study performed the human eye biopsy confirming directly the expression of TSLP and its downstream molecules in different types of patients with allergic conjunctivitis." (PMID 27504196, 2016). "The present study sought to investigate the expression of TSLP and its downstream molecules IL-4, IL-13, and IL-5 in the conjunctival tissue of patients with allergic conjunctivitis and tear." (PMID 27504196, 2016). "Immunohistochemistry, real-time PCR, and Luminex technology were used to measure the expression of TSLP, IL-4, IL-5, and IL-13 in the tears and conjunctival cell of the normal population and patients with three types of allergic conjunctivitis." (PMID 27504196, 2016). "Immunohistochemical staining confirmed an increase in TSLP, IL-4, IL-5, and IL-13 production in the eyes with various types of allergic conjunctivitis." (PMID 27504196, 2016). "However, identifying the roles of TSLP and its downstream molecules in different types of allergic conjunctivitis needs more research." (PMID 27504196, 2016). "Thus, TSLP has a role to play in allergic conjunctivitis and allergic keratoconjunctivitis." (PMID 38541674, 2024). "In allergic conjunctivitis, a disease also affecting a stratified squamous epithelium, TSLP is expressed within the differentiated compartment of the conjunctival epithelium, suggesting that contact with allergens at the barrier surface may play a direct role in regulating TSLP expression." (PMID 26992000, 2016).
childhood asthma (6 papers, 2011 to 2025). "Another multicentre prospective study reported that higher nasopharyngeal airway type 2 cytokine (IL-4, IL-5, IL-13, and TSLP) levels in infants with HRV infection alone were associated with a greater risk of developing childhood asthma." (PMID 40852413, 2025). "The joint effect of TSLP rs2289277 and rs11466750 genotypes and TSLP (sfTSLP and lfTSLP) expression in nasal epithelial cells is associated with increased childhood asthma." (PMID 37628907, 2023). "The study conducted in the birth cohort from the Urban Environment and Childhood Asthma (URECA) found that the early presence of circulating TSLP was significantly associated with reduced incidence of recurrent wheeze in those children not sensitized to aeroallergen." (PMID 36694181, 2023). "In the context of the induction of childhood asthma, a role for AEC-derived TSLP in the induction phase is strongly supported by in vitro studies." (PMID 22574070, 2011). "To date, however, there are no reported in vitro studies using AEC isolated from children nor have there been studies on the role of TSLP in an animal model of childhood asthma." (PMID 22574070, 2011).
Crohn disease (6 papers, 2010 to 2025). A gastrointestinal disorder characterized by chronic inflammation involving all layers of the intestinal wall, noncaseating granulomas affecting the intestinal wall and regional lymph nodes, and transmural fibrosis. "In patients with Crohn’s disease, TSLP is found to be downregulated compared with controls, further implicating TSLP as playing a pivotal role in suppressing inflammation in the colon." (PMID 37427591, 2023). "Finally, TSLP expression is reduced in colonic tissue of Crohn’s disease patients and can be correlated to the failure of these patients to promote tolerogenic DCs in the gut." (PMID 26546058, 2015). "Moreover, Crohn’s disease patients have shown a reduction of intestinal TSLP expression." (PMID 26546058, 2015). "Production of TSLP by IEC is pivotal in maintaining gut homeostasis and indices on lower expression of Tslp in primary IEC from Crohn's disease patients than in healthy individuals have been reported." (PMID 20085657, 2010).